EIF4E (eukaryotic translation initiation factor 4E)
Diseases named in the same sentence as EIF4E in open-access papers (continued):
Sharing a sentence is not in itself a finding about the gene and the disease.
tumor (continued). "Notably, SMAPs promoted 4E-BP1–dependent apoptosis in tumor cells and potentiated 4E-BP1 function in the presence of ERK or mTOR inhibitors, agents that rely on inhibition of eIF4E-dependent translation for antitumor activity." (PMID 39869680, 2025). "To determine whether the CalPegA-S55746 combination impacted mRNA translation initiation in vivo, we used immunoblotting to assess the phosphorylation status of eIF4E and 4EBP1 in bone marrow cells from AML45-luc tumor-bearing mice." (PMID 39684800, 2024). "In contrast with 4E‐BP1 hypophosphorylation, skeletal muscle eIF4E protein levels were significantly elevated in tumor‐bearing rats, a response that was not mirrored in the heart." (PMID 39294861, 2024). "One study revealed that eIF4E expression was upregulated in HCC tissues compared with nontumor tissues and was associated with tumor number, overall survival, and the disease-free survival rate." (PMID 39199296, 2024). "Furthermore, it has been reported that outside of serine biosynthesis, PHGDH enhances mRNA translation by interacting with eIF4A1 and eIF4E, thereby promoting PDAC tumor growth." (PMID 38951899, 2024). "Collectively, these data suggest that MAPK4 promotes MNK1/2-mediated eIF4E S209 phosphorylation; however, unexpectedly, eIF4E S209 phosphorylation does not play a notable role in MAPK4 promotion of PDK1 protein expression or tumor growth." (PMID 37531320, 2023). "Meanwhile, AKR1B1 inhibition could block the mTOR pathway activation by activating 5′ adenosine monophosphate-activated protein kinase (AMPK) as it inhibits the phosphorylation of mTOR, Raptor, eIF4E, S6K, and 4E-BP1, thus inhibiting tumor growth." (PMID 37751590, 2023). "Immunohistochemistry (IHC) analyses showed that PI3K, AKT, p-AKT, p-mTOR, p-4E-BP1, P70S6K1, p-P70S6K1, eIF4E, and p-eIF4E proteins were significantly overexpressed in tumor tissues compared to adjacent non-tumoral tissues (p < 0.05 for all)." (PMID 37047267, 2023). "Reassuringly, Eif4e, another MYC target gene, was also upregulated in Myc-R26Met tumours." (PMID 36433941, 2022). "As a control, the caspase-3 activity in tumor tissue was not changed by IKE in the absence or presence of EIF4E or ALDH1B1." (PMID 36274088, 2022). "Emerging data has suggested that tumor cells overexpress Exportin-1 (XPO1), which is the major nuclear export protein in the cell mediating the efflux of tumor suppressor proteins and the methyl-guanine capped mRNA binding protein eIF4E." (PMID 34562230, 2022). "Furthermore, CPT and imatinib treatment significantly inhibited tumour growth of imatinib resistant K562 cells in vivo through suppression of STAT3 and eIF4E signalling pathways." (PMID 34214017, 2021). "In addition, silencing mTORC1 and eIF4E upregulated Beclin-1 and LC3 and decreased the expression of HIF-1α, thereby inhibiting tumor cell proliferation." (PMID 34917504, 2021). "Another advantage of SBI-756 compared to TOR-KI treatment is its ability to suppress cap-dependent translation among cells lacking 4E-BP1, a finding relevant to tumours with reduced ratio of 4E-BPs to eIF4E." (PMID 33318657, 2021). "This review highlights recent studies on lncRNAs in the regulation of protein translation by modulating the translational factors (i.e, eIF4E, eIF4G, eIF4A, 4E-BP1, eEF5A) and signaling pathways involved in this process as wells as their potential roles as tumor suppressors or tumor promoters." (PMID 33672592, 2021). "Finally, pharmacologic inhibition of phosphorylated eIF4E reduced MDSC abundance and immunosuppressive function, and synergized with anti-PD-1 immunotherapy to delay tumor growth and metastasis." (PMID 32731503, 2020).
tumor (continued). "Mechanism of action studies performed in vitro and on mice tumor samples suggest that the combination PIM-Pd inhibits protein translation processes through the convergent inhibition of c-Myc and mTORC1, which subsequently disrupts the function of eIF4E." (PMID 32987735, 2020). "In the present study, significantly lower eIF4E and higher p-eIF4E expressions were observed in ccRCC patients who did not experience tumour recurrence than in those who did." (PMID 31258849, 2019). "In our study, we observed lower expression levels of p-PI3K and p-eIF4E in patients with tumor recurrence than in those without recurrence." (PMID 31756179, 2019). "Furthermore, a research group investigated the effect of hypoxia and serum deprivation, two conditions often present in the tumor microenvironment, on the proteome of U87MG cells and found that eIF4E was overexpressed under these conditions." (PMID 31795417, 2019). "In addition, tumour cell pseudopod-specific proteins (AHNAK, Septin-9, eIF4E, and S100A11) were identified from the transcriptome/proteome analysis and closely for pseudopod formation, actin cytoskeleton dynamics, and tumour cell migration and invasion." (PMID 30504808, 2018). "To establish whether MNK2-regulated 4EBP1/eIF4E and ERK/eIF4E pathway promote tumor growth and metastasis in NSCLC, we used RT-PCR and western bolt analysis to measure mRNA and protein levels." (PMID 28878291, 2017). "Hence, the various eIF4E/4E-BP1 ratios, reflecting tumor grade, have implications for the response to both metformin and asTORi." (PMID 28881582, 2017). "The statistically significant correlation between more marked expression of eIF4E with higher tumor grade and poor prognosis in DIA had not been previously reported." (PMID 27440383, 2016). "These patient tumor samples are determined as eIF4E, VEGF-C, MMP-2 and E-cadherin positive or negative, respectively." (PMID 27907907, 2016). "The fact that these five genes (MTHFD2, EIF4E, RMI1, CAV1 and HIF1A) are all very relevant in tumor biology further emphasizes a role of Wig-1 in the regulation of cell cycle and cell proliferation, as well as tumor onset, progression and metastasis." (PMID 26672765, 2016). "The expression of eIF4E was assessed semi-quantitatively as follows; negative (< 10% of cells eIF4E positive) or positive (>10% tumor cells eIF4E positive)." (PMID 25839159, 2015). "Therefore, in the present study inhibiting FGFR3 or eIF4E selectively suppressed the expression of FGFR3 or eIF4E regulated proteins and substantially repressed tumor growth on tumor models." (PMID 26078354, 2015). "Mnk1 and Mnk2 knock-out or knock-in mice, in which Ser209 was replaced by alanine, showed no eIF4E phosphorylation and significantly attenuated tumour growth." (PMID 22392765, 2012). "The intra-tumor activity of eIF4E was not different between the eIF4E-positive and -negative margin groups." (PMID 21513566, 2011). "In tumour xenograft models, eIF4E ASOs inhibited tumour growth without any detectable changes in body weight or liver function." (PMID 21772331, 2011). "Disappointingly and in contrast to our in vitro work, we found estimated eIF4E activity did not predict response to mTOR inhibition as assessed by change in tumour cell proliferation." (PMID 21320304, 2011). "Tumour stroma and normal tissue were negative for eIF4E, 4E-BP1 and 4E-BP2, whereas very occasional low-intensity staining for p4E-BP1 was noted in normal epithelial cells." (PMID 19367274, 2009). "Models that most accurately reflected the data included eIF4E scores rather than dichotomised data, showing the value of scoring proportion and intensity of positive tumour cells." (PMID 19367274, 2009). "One cell line (SKRC-39) expressed high levels of eIF4E in the absence of upstream signalling, and one tumour (#12) showed a very similar biochemical pattern, with high eIF4E but no detectable EGFR or phospho-Erk." (PMID 15956968, 2005).
tumor (continued). "It has been suggested that eIF-4E may regulate expression of genes including angiogenic factors such as VEGF and b-FGF as well as subsequent tumour growth." (PMID 12189553, 2002). "Phosphorylation of eIF4E being a rate-limiting step in the formation of the eIF4F translation initiation complex, the degradation of MNK1/2 by VNLG-152R and its analogs impedes dysregulated translation in TNBC cells, resulting in the inhibition of tumor growth." (PMID 37766871, 2023). "In particular, the eukaryotic translation initiation factor 4E (eIF4E) is hyperactivated via phosphorylation downstream of the MAPK-interacting serine/threonine kinases (MNKs) and by mTOR-dependent inactivation of its negative regulators—tumor-suppressive eIF4E-binding proteins (4E-BPs)." (PMID 35267591, 2022). "Additionally, a significant difference in eIF4AI and eIF4E expression was absent in this cohort when stratified based on tumor stages 1–2 versus 3–5 (eIF4AI: p = 1.000; eIF4E: p = 0.451)." (PMID 33540613, 2021). "Phosphorylated eIF4E preferentially upregulates translation of a specific set of transcripts involved in epithelial-mesenchymal transition (EMT) and metastasis, which supports the observation of increased tumor invasiveness and distant metastasis in mutant mice." (PMID 35048066, 2021). "In fact, several studies have shown that the oncogenic activity of eIF4E can be targeted by inhibiting MNK1/2-induced phosphorylation of eIF4E at serine 209 in different malignancies, including AML, which leads to potent anti-tumor responses in vitro and in vivo." (PMID 31903169, 2019). "A 4E-antisense oligonucleotide to reduce the expression of eIF4E was shown to inhibit tumor growth in a prostate cancer xenograft model and was safe in humans in a Phase I clinical trial, though it did not demonstrate anti-tumor activity as a single agent." (PMID 29799508, 2018). "Notably, MNK kinases are required for eIF4E phosphorylation at Ser209 in tumor cells, but not normal cells." (PMID 27926520, 2017). "As far as 4EBP1 and p70S6K are concerned, 4EBP1 takes part in controlling ribosome protein synthesis,and therefore, non-phosphorylated 4E-BP1 binds eIF4E and impedes formation of the initiation complex, blocking translation, favoring apoptosis and inhibiting tumor cell survival and proliferation." (PMID 25165983, 2014). "For eIF4E cohort, 10 tumor cases could not be stained as negative expression, and positive rate was 92.8%, with 74 high expression." (PMID 24839543, 2014). "A subset of tumours and cell lines expressed elevated eIF4E in the absence of upstream activation." (PMID 15956968, 2005). "In line with this, overexpression of 4EBP1AA in HeLa cells promoted tumor growth relative to control (EV) HeLa cells when injected into the flanks of immunocompromised mice, which was not the case with overexpression of the eIF4E-non-binding mutant 4EBP1AA, YL." (PMID 38744825, 2024). "Thus, HSP90/AXL/eIF4E-regulated UPR that underpins adaptive resistance to MTA and trametinib also regulates intratumor heterogeneity of KRAS-mutant lung tumor cells that occurs under pathological conditions, extrapolating our findings to a generalized principle that governs tumor progression." (PMID 31431614, 2019). "We concluded that high estimated eIF4E activity may, in fact, predict tumour response to everolimus; however this response is not the expected reduction in proliferation, but is development of changes in eIF4E regulation, presumably to promote everolimus resistance." (PMID 21320304, 2011). "In a phase I dose escalation study, a reduction in eIF4E expression level was detected in tumour biopsies following LY2275796, although no tumour response was observed." (PMID 40805230, 2025).
tumor (continued). "In the subgroup analysis, expression levels of eIF4E, p-PI3K, p-AKT, p-mTOR, p-4EBP1, p-eIF4E, p-S6K1, and p-S6R in the tumor specimens of patients with or without recurrence were analyzed using IHC staining and quantified by semi-quantified scoring systems." (PMID 31756179, 2019). "Taken together, these results clearly show that our most efficacious Mnk1/2 degrader, VNLG-152R exerts remarkable anti-tumor and anti-metastatic effects in in vivo TNBC models via inhibiting Mnk-eIF4E and mTORC1 signaling without any significant toxicity." (PMID 30832411, 2019). "eIF4E is overexpressed in malignant breast cancer tumor lines MDA-MB-435, MDA-MB-231, and MCF-7, but not in non-tumor cells (MCF-10A) or epithelial cells from the milk of a nursing mother." (PMID 19134194, 2009).
infection (101 papers, 2007 to 2025). The state of being infected such as from the introduction of a foreign agent such as serum, vaccine, antigenic substance or organism. "The protyvirus-derived viral genome-linked protein (VPg) associates with host eIF4E for successful infection." (PMID 40749075, 2025). "Potyviruses require eukaryotic translation initiation factor 4E (eIF4E) and its iso form (eIF(iso)4E) for infection via viral genome-linked protein (VPg-eIF4E) interactions." (PMID 41523156, 2025). "Faint multiplication in plants with resistant eIF4E alleles suggests that viruses can use these alleles for multiplication, although with very low efficiency, as indicated by a low infection level." (PMID 36844044, 2023). "After the virus enters a plant, the VPg encoded by the virus interacts with the eIF4E of the plant to complete virus replication and infection." (PMID 37570959, 2023). "The absence or mutation of eIF4E in host plants can lead to recessive resistance and hinder infection by viruses in the family Potyviridae." (PMID 37570959, 2023). "The cap-binding protein (also known as eukaryotic translation initiation factor 4E (eIF4E)) encoding gene is one of the components of susceptibility as it plays an essential role in the infection cycle of potyviruses in peppers and other crops." (PMID 35891620, 2022). "The VPg protein of PVY interacts with the translation initiation factor eIF4E of the host that works as a susceptibility factor during infection." (PMID 35910230, 2022). "Eukaryotic translation initiation factor 4E (eIF4E) plays a key role in the infection of potyviruses in susceptible plants by interacting with viral genome-linked protein (VPg)." (PMID 33809985, 2021). "Since the eIF4E protein is a host susceptibility factor that plays a pivotal role in potyviral infection, its recessive resistance alleles are considered to lack the function that supports infection." (PMID 33362728, 2020). "Resistance to infection can sometimes be conferred by expressing structural variants of eIF4E postulated to impede the stage of viral translation initiation." (PMID 31906869, 2020). "For instance, the eukaryotic translation initiation factor 4E (eIF4E) and 4G (eIF4G) in eukaryotes are essential host factors required for infection by many viruses including Potyvirus and mutations of these gene results in recessive resistance in crop plants." (PMID 30186289, 2018). "A similar interaction of the plant potyvirus VPg with eIF4E has also been reported and is known to determine the relative susceptibility of plant species to infection (for review, see Ref." (PMID 24928504, 2014). "eIF4E and/or eIF(iso)4E were also identified as susceptibility factors required for infection of cucumoviruses, bymoviruses and carmoviruses." (PMID 23382802, 2013). "We hypothesized that PVY RB might recruited one or more specific eIF4E isoforms to establish productive infection in va tobacco, which lack the PVY-susceptible eIF4E1-S." (PMID 40641643, 2025). "Thus, mutating eIF4E genes can alter this interaction and prevent the virus from exploiting the host cellular machinery, thereby protecting the host from infection (i.e., recessive resistance)." (PMID 39519021, 2024). "During these subliminal infections, variants of the virus could appear with mutations in VPg, allowing the virus to use an alternative eIF4E isoform more efficiently." (PMID 36844044, 2023). "Considering that the potyviral interaction with backup eIF4E isoform is suboptimal, this quantitative increase or decrease in translational efficiency may lead to a qualitative difference in the infection course, i.e., susceptibility or resistance." (PMID 36844044, 2023). "The dysfunction of SwCMp VPg-containing PPV chimera in A. thaliana was suggested to be caused by a defect in VPg/eIF(iso)4E interaction, because mutations promoting infection in this host resembled those detected in potyviruses escaping eIF4E/(iso)4E- based resistance." (PMID 33920394, 2021).